GDF15 (growth differentiation factor 15)
Diseases named in the same sentence as GDF15 in open-access papers (continued):
Sharing a sentence is not in itself a finding about the gene and the disease.
heart disease (continued). "It has also been reported that GDF-15 plays a protective role in heart disease, which may be attributed to the anti-apoptotic, anti-inflammatory, or anti-hypertrophic effects demonstrated in animal models." (PMID 27154403, 2016). "Given the value of GDF-15 as a marker of heart disease and cardiovascular risk and the prevalence of major adverse cardiovascular events associated with the post-CPB period, it seems important to measure GDF-15 levels in patients undergoing CABG with CPB so as to improve diagnosis and follow-up." (PMID 25171167, 2014). "For example, GDF15 is induced and seen as a biomarker in patients with heart disease." (PMID 23799024, 2013). "However, separately from intrinsic cardiac disease, GDF15 may be a predictive myocardial biomarker for cardiac injury or flares chronic, systemic inflammatory conditions." (PMID 40019842, 2025). "In addition to blood pressure, blood lipids and exercise tests, molecular biomarkers such as circulating cardiac troponin T (cTnT), N-terminal pro-B-type natriuretic peptide (NT-proBNP) and growth-differentiation factor 15 (GDF-15) are valuable tools in the diagnosis of preclinical heart disease." (PMID 35796791, 2022). "IGFBP7 and the other 2 biomarkers, GDF-15 and P1NP, were chosen since they covered different aspects of cardiac diseases, such as inflammation, apoptosis, fibrosis, and were described as specifically linked to one or more cardiac phenotypes." (PMID 34217226, 2021). "Growth differentiation factor-15 (GDF-15), Cystatin C and C-reactive protein (CRP) have been discussed as biomarkers for prediction of cardiac diseases." (PMID 29771963, 2018). "Cardiac and circulating levels of both GDF15 and ANP/BNP are highly elevated in many forms of heart disease." (PMID 28572090, 2017). "GDF-15 and ST2 are emerging biomarkers, which may have the same potential as natriuretic peptides to impact the way cardiac disease is evaluated and managed." (PMID 36001499, 2022). "In microalbuminuric T2D patients with normal kidney function and without known cardiac disease, higher concentration of GDF-15 predicted decline in renal function, CV events and all-cause mortality." (PMID 29698460, 2018). "In addition, we find that children with concomitant heart disease and FTT have elevated plasma GDF15." (PMID 28572090, 2017). "Importantly, plasma GDF15 level is further significantly increased (another 80% higher) in children with concomitant heart disease and FTT than those with heart disease but normal body weight, supporting elevated GDF15 as an underlying mechanism linking pediatric heart disease and FTT." (PMID 28572090, 2017). "Previous studies have reported that higher expression levels of GDF-15 could predict deteriorating conditions for heart disease patients, particularly ACS patients, independent of troponin or BNP levels." (PMID 27154403, 2016).
neurodegenerative disease (22 papers, 2018 to 2026). A disorder of the central nervous system characterized by gradual and progressive loss of neural tissue and neurologic function. "GFRAL is a receptor of GDF15 which is implicated in several neurodegenerative diseases and with poor cognitive performance." (PMID 40665476, 2025). "The diagnostic utility of GDF15 had a good sensitivity of 0.90 and had a good specificity of 0.77 in distinguishing neurodegenerative disease from health." (PMID 35068064, 2022). "And serum levels of GDF15 were a better marker for diagnostic utility of neurodegenerative diseases." (PMID 35068064, 2022). "Compared with the healthy control, SROC for sensitivity and specificity indicated that the serum levels of GDF15 were a better marker for diagnostic utility of neurodegenerative disease." (PMID 35068064, 2022). "The purpose of this systematic review and meta‐analysis was to quantitatively assess the association between the GDF15 levels and neurodegenerative disease." (PMID 35068064, 2022). "First, we only investigated the diagnostic validity using the SROC curve of GDF15 levels for total neurodegenerative disease." (PMID 35068064, 2022). "Two studies reported the diagnostic value of GDF15 for neurodegenerative disease in different genders." (PMID 35068064, 2022). "Concerning AD, limited data are available on the association between GDF-15 and neurodegenerative diseases." (PMID 33131010, 2021). "And serum levels of GDF15 were a better marker for diagnostic utility of neurodegenerative disease." (PMID 35068064, 2022). "In particular, some studies suggested that high circulating levels of GDF15 are associated with the risk of developing AD, as well as other neurodegenerative diseases, and considered this protein as a promising diagnostic biomarker and therapeutic target of several neurodegenerative diseases." (PMID 36698863, 2022). "GDF-15 might be linked with neurodegeneration and affects the risk of neurodegenerative diseases." (PMID 34484296, 2021). "Despite known links between inflammation and pathological aging outcomes, studies have found inconsistent associations between peripheral levels of inflammatory proteins, including CRP and GDF15, and markers of brain health and neurodegenerative disease." (PMID 41274863, 2025). "In this regard, the finding in animal models that treatment with GDF-15 has neuroprotective and neurotrophic effects on GCs is of great significance, underscoring the potential importance of this cytokine in GC degenerative diseases." (PMID 41357352, 2025). "Given the complex and multifaceted effects of circulating GDF15 [1283–1285] in cerebrovascular and neurodegenerative diseases, further mechanistic studies are needed to elucidate how GDF15 influences cellular pathways and contributes to long-term brain health." (PMID 40407975, 2025). "In human studies, GDF15 levels were measured in biological fluids (n = 50) and/or post-mortem CNS tissue (n = 3) of individuals affected by neurodegenerative disease or injury." (PMID 39737171, 2024). "This variability extends to factors like method of induced neurodegenerative disease or injury, method of GDF15 modulation, types of outcomes measured, spatial and temporal assessment and animal age, all impacting functional outcomes." (PMID 39737171, 2024). "This review systematically examines literature about GDF15 in neurodegenerative diseases and neurotrauma." (PMID 39737171, 2024). "In doing so, we provide the first systematic examination of literature on GDF15 in relation to neurodegenerative physiopathology and highlight the potential for GDF15 as a viable therapeutic target across several neurodegenerative diseases." (PMID 39737171, 2024). "The second aim of this systematic review was to assess GDF15 levels as a biomarker in individuals with neurodegenerative disease or injury." (PMID 39737171, 2024).
neurodegenerative disease (continued). "Overall, there is sufficient evidence identifying GDF-15 as a cytokine that should be studied further as a neurotrophic factor with potentially beneficial effects in human neurodegenerative diseases." (PMID 39683685, 2024). "Since it has been indicated that high levels of GDF-15 are found in individuals with neurodegenerative diseases, GDF-15 has potential as a biomarker for diagnosis and prognosis." (PMID 39000435, 2024). "GDF-15 is generated in the choroid plexus, damaged neurons and microglial cells and found to be elevated in persons with neurodegenerative disease." (PMID 37371414, 2023). "We found that GDF15 levels were higher in patient with neurodegenerative disease than that in the healthy people." (PMID 35068064, 2022). "The pooled results of the random effect model indicated GDF15 levels were significantly higher in patients with neurodegenerative disease than healthy people (SMD = 0.92, 95% CI: 0.44–1.40, Z = 3.75, p < 0.001)." (PMID 35068064, 2022). "Higher‐quality studies on the relationship between the levels of GDF15 and neurodegenerative disease were needed aiming to better evaluate its clinical prognostic and diagnostic value." (PMID 35068064, 2022). "Four studies reported the serum level of GDF15 in patients with neurodegenerative disease (three studies for PD, one studies for MSA)." (PMID 35068064, 2022). "Our results found that GDF15 levels were higher in patient with neurodegenerative disease than that in the healthy people." (PMID 35068064, 2022). "Previous observational studies have suggested that associations exist between growth differentiation factor 15 (GDF-15) and neurodegenerative diseases." (PMID 34484296, 2021). "Elevated circulating GDF15 is observed in various pathological conditions, including cardiovascular disease, cancer, metabolic syndrome, and neurodegenerative diseases, making it an important biomarker for age-related diseases and overall mortality risk [1005, 1258, 1259]." (PMID 40407975, 2025). "GDF-15, also known as macrophage inhibitory cytokine-1, is expressed in most organs, including damaged neurons, and it is a marker of mitochondrial dysfunction and elevated in myopathies and neurodegenerative disease." (PMID 37371414, 2023). "In conclusion, this meta‐analysis found GDF15 as a potential marker of neurodegenerative disease." (PMID 35068064, 2022). "The pooled results of the random effect model indicated GDF15 levels were significantly higher in patients with neurodegenerative disease than healthy people (SMD = 0.92, 95% CI: 0.44–1.40, Z = 3.75, p < 0.001), with high heterogeneity among studies (I2 = 86.1%, p < 0.001)." (PMID 35068064, 2022). "GDF15 levels were higher in patients with neurodegenerative disease than healthy people." (PMID 35068064, 2022). "In additions, abnormal concentrations of GDF15 are also believed to be closely correlated with neurodegenerative diseases and may be a potential biomarker for early diagnosis and prognosis." (PMID 35068064, 2022). "GDF15 is produced in response to mitochondrial and inflammatory stressors and is involved in many ARDs, such as cancer, T2D, obesity, and cardiovascular and neurodegenerative diseases." (PMID 33131010, 2021). "GDF15 may be a potential biomarker for neurodegenerative diseases." (PMID 35068064, 2022). "All these data suggest that GDF15 could be a possible biomarker for neurodegenerative diseases." (PMID 33131010, 2021). "Thus, GDF15 plasma levels may be associated to some neurodegenerative diseases, but not to AD." (PMID 33131010, 2021). "By analogy with the amyloid-tau-neurodegeneration (A/T/N) classification in neurodegenerative diseases, a similar approach could be considered for mitochondriopathies, including biomarkers for metabolic disturbance (FGF21), apoptosis/cellular stress (GDF15) and lysosomal dysfunction (CHIT1)." (PMID 39891741, 2025).
myopathy (16 papers, 2014 to 2025). A disease of the muscle in which the muscle fibers do not function properly. "These previous findings suggest the potential use of GDF-15 as a diagnostic marker to differentiate myopathies." (PMID 38058222, 2025). "Of note, it has been observed that individuals with myopathies linked to mitochondrial dysfunction exhibit elevated levels of GDF-15 in their serum." (PMID 38058222, 2025). "In four participants with the m.8344A > G mutation with myopathy, GDF-15 levels were also elevated at 2,428 ± 1,252 pg/mL." (PMID 35071983, 2021). "We have seen in primary mitochondrial disorders associated with overt myopathy that GDF15 expression is massively upregulated in skeletal muscle and this is associated with an increase in circulating levels." (PMID 31801546, 2019). "GDF-15 is regarded as a mitokine and a known biomarker for mitochondrial dysfunction, where it is found to be elevated in various myopathies." (PMID 37152099, 2023). "This corresponded to elevated plasma levels of GDF15, starting from the early myopathy stage and increasing with age (3‐, 6‐, and 16‐fold change at 50, 100, and 200 days, respectively)." (PMID 37222423, 2023). "The mean circulating concentration of GDF-15 was almost identical in healthy children (mean = 350.3, SEM = 21 pg/mL) and in myopathic non-mitochondrial controls (349.1 pg/mL) whereas FGF-21 was higher in children with myopathy (136.1 pg/mL) than in unaffected controls (77.6 pg/mL)." (PMID 26867126, 2016). "We have no biomarkers (FGF-21 and GDF-15) follow-up data; their role in future trials is still unclear, although in TK2 myopathy a reduction in GDF-15 levels after treatment has recently been observed." (PMID 35980466, 2022).
inflammation (14 papers, 2017 to 2025). Aberrant reaction of the microcirculation characterized by movement of fluid and leukocytes from the blood into extravascular tissues. "GDF15 (growth differentiation factor 15) is emerging as a key biomarker for predicting systemic aging and all-cause mortality and is also closely associated with chronic inflammation and immune decline in older adults." (PMID 41516233, 2025). "In this respect, increased expression GDF-15—as observed in lungs of smokers and patients with COPD contributes to cigarette smoke -induced pulmonary inflammation." (PMID 34920697, 2021). "The interplay of prostatic inflammation with NF‐κB and GDF‐15 expression in early prostate cancer development is unclear from our study results, although our findings suggest GDF‐15 may repress chronic inflammation in the benign prostate." (PMID 33784024, 2021). "Growth differentiation factor-15 (GDF-15) and its receptor GDNF family receptor α-like (GFRAL) are potential molecular targets of metformin, involving in macrophage activation and differentiation of cardiovascular inflammation." (PMID 33115406, 2020).
bacterial infection (8 papers, 2020 to 2026). "This aligns with previous data linking GDF‐15 to LPS and CRP levels in patients with alcohol‐associated hepatitis, as well as experimental data showing GDF‐15 upregulation following LPS injection in mice, mimicking bacterial infections." (PMID 41555670, 2026). "Recently, it has been demonstrated that GDF15 is necessary for tolerance to inflammation induced by viral or bacterial infections." (PMID 32477368, 2020). "In summary, the present study is the first to demonstrate that treatment with the S1PR2 antagonist (JTE013) enhanced TGFβ/Smad and Akt signaling and increased VEGFA, PDGFA, and GDF15 gene expressions in murine BMSCs with or without bacterial infection." (PMID 36834810, 2023).
hematological malignancies (7 papers, 2015 to 2023). "The association between GDF-15 and hepcidin was first defined in hematologic diseases." (PMID 27642607, 2016). "In summary, we have conducted the most extensive survey to date of the relationship between the elevated levels of GDF15, which are a consistent feature of the β‐thalassaemias and the systemic complications of this important blood disorder." (PMID 36806122, 2023). "In this study, we demonstrated that the concentration of serum GDF15 was significantly increased in patients with various hematologic malignancies in comparison with healthy controls." (PMID 26276681, 2015). "To assess the potential roles of GDF15 in hematologic malignancies, we measured its serum levels in patients with these diseases." (PMID 26276681, 2015). "In this study, we evaluated serum levels of GDF15 in patients with various hematologic diseases." (PMID 26276681, 2015). "soluble urokinase plasminogen activator receptor (suPAR) and growth differentiation factor-15 (GDF-15) have been determined as endothelial injury indices in various clinical settings in both hematological and non-hematological diseases." (PMID 38203404, 2023). "Among the hematologic diseases that we evaluated, PMF showed particularly high serum GDF15 concentrations." (PMID 26276681, 2015). "Apart from this study there is little evidence for the involvement of GDF-15 in hematological malignancies." (PMID 32508832, 2020).
prostate (7 papers, 2015 to 2025). "GDF-15 preserved Klotho expression during acute kidney injury and fibrosis, indicating a relationship between GDF-15 and Klotho expression." (PMID 40362229, 2025). "One of the most intriguing cytokines that may play a role in prostate carcinogenesis is GDF-15; GDF-15 has pleiotropic functions at all stages of tumorigenicity and is suggested as a marker to predict aggressive PCa disease." (PMID 36230513, 2022).
neuromuscular disease (5 papers, 2020 to 2025). "Elevated GDF15 levels have been reported as a biomarker of neuromuscular diseases of genetic origin caused by alterations in the mitochondrial genome." (PMID 33329017, 2020). "It is worth mentioning that, beyond exercise, the blood levels of GDF15 and FGF21 are also increased in pathological contexts, such as in patients affected by neuromuscular diseases caused by mitochondria DNA mutations." (PMID 33329017, 2020). "In conclusion, serological assessment in a large cohort of patients with neuromuscular diseases suggests that CHIT1 levels are significantly elevated in mitochondriopathies and may complement the established biomarkers FGF21 and GDF15." (PMID 39891741, 2025).
retinopathy (5 papers, 2020 to 2022). "Investigations have shown a positive association between GDF-15 serum concentrations and diabetes risk of retinopathy with higher levels associated in proportion with the grade level of retinopathy." (PMID 38983558, 2022). "It is necessary to explore the underlying mechanisms between GDF-15 and retinopathy in individuals with type 2 DM in the future research." (PMID 33239667, 2020). "Moreover, higher levels of GDF-15 have been associated with diabetic nephropathy, peripheral neuropathy and proliferative retinopathy rather than with non-proliferative retinopathy in patients with T1DM." (PMID 33504108, 2021). "Hence, it is presumed that these might be partially responsible for the observed relationship between GDF-15 and retinopathy." (PMID 33239667, 2020). "Moreover, patients with proliferative retinopathy had higher GDF-15 concentrations as compared with patients with nonproliferative retinopathy." (PMID 31936869, 2020).
immune dysfunction (4 papers, 2020 to 2023). "Recently, GDF‐15 was found to mediate aging‐related anti‐inflammatory effects in both humans and mice, lending some credence to the idea that the cytokine is a potential mediator of innate immune dysfunction in aged individuals." (PMID 33738380, 2021).